TIMP1 (TIMP metallopeptidase inhibitor 1)
Diseases named in the same sentence as TIMP1 in open-access papers (continued):
Sharing a sentence is not in itself a finding about the gene and the disease.
heart disease (13 papers, 2013 to 2025). "Tissue metalloproteinase inhibitor 1 (Timp1) is commonly used as a cardiac fibrosis biomarker, whose levels are associated with cardiac fibrosis in patients with heart disease." (PMID 35954191, 2022). "The MMP‐9 and TIMP‐1 levels are significantly elevated in acute critical care settings with increased short-term mortality risk, especially in patients with underlying heart disease." (PMID 31932967, 2021). "A previous study has shown that levels of TIMP-1 increase with age and also increases the risk of heart disease." (PMID 31178745, 2019). "In a subgroup analysis, plasma MMP‐9 (p = 0.002) and TIMP‐1 (p = 0.01) levels upon admission to the ICU as well as SAPSII (p < 0.0001) were independent predictors for 30-day survival in the patient group with cardiac disease only." (PMID 31932967, 2021). "In patients with underlying cardiac diseases, MMP‐9 (p = 0.002) and TIMP‐1 (p = 0.01) were independent predictors of survival (Cox regression)." (PMID 31932967, 2021). "Univariate analyses revealed that increasing age, male sex and heart disease as well as increasing levels of MMP-9 and MMP-9/TIMP-1 ratio were associated with an increased risk for death, expressed as Hazard Ratio (HR, 95% CI)." (PMID 29650051, 2018). "With this new information on the role of TIMP-1 in the process of fibrosis, the discovery of targeted therapy may prove beneficial in limiting this process in patients with heart disease." (PMID 37893149, 2023). "Also, studies by Heymans in human cardiac disease and Wang in rat lungs reported upregulated TIMP1 gene expression during fibrosis." (PMID 36032279, 2022). "The prognostic significance of (early) TIMP‐1 levels has been extended to a heterogeneous group of critically ill patients and further support the predictive value of MMP‐9 levels on short-term mortality, especially in patients with underlying cardiac disease." (PMID 31932967, 2021). "Cigarette smoking, a predominant factor for lung tumorigenesis, was reported to decrease TIMP-1, TIMP-2, or TIMP-3 expression in patients with heart disease or NSCLC." (PMID 33126605, 2020). "In non-COPD, male sex, burden of smoking, heart disease and MMP-9/TIMP-1 ratio increased the risk for death, and serum concentration of TIMP-1 had a protective effect." (PMID 29650051, 2018). "In non-COPD, male sex, age, burden of smoking, heart disease and MMP-9/TIMP-1 ratio were associated with increased risk for death, while increased TIMP-1 was protective." (PMID 29650051, 2018).
inflammation (11 papers, 2013 to 2023). Aberrant reaction of the microcirculation characterized by movement of fluid and leukocytes from the blood into extravascular tissues. "Similarly, increased levels of TIMP-1, a member of tissue inhibitors of metalloproteinases (TIMP1-4) group, have been reported in fibrotic lesions of mice with chronic inflammation and CD patients while TIMP-1 deficiency has been shown to weaken the development of fibrosis." (PMID 30619271, 2018). "In addition to a-Sma, matrix metalloproteinases such as Mmp9 and Timp1 are also involved in the development and progression of liver inflammation and fibrosis." (PMID 31921324, 2020). "The ELA group exhibited increases in alveolar neutrophil infiltration, the numbers of TNF-α, MAC-2, MMP-9, MMP-12, TIMP-1, eNOS, and iNOS-positive cells and the volume fraction of the 8-iso-PGF2 α, suggesting the presence of lung inflammation, remodeling, and oxidative stress processes." (PMID 27528793, 2016).
neurological diseases (10 papers, 2014 to 2025). "In patients with end-stage neurological disease, chronic activation of astrocytes by IL-1β caused downregulation of TIMP-1 mRNA and protein expression in CSF and brain tissues." (PMID 30062663, 2019). "Similarly, the roles of TIMP1 and SERPINE1 in inflammation and tissue remodeling have been documented in various neurological disorders, but their specific contributions to ICH progression are less explored." (PMID 38927081, 2024). "Among them, LCN2, TIMP1, S100A8/9, and PRDX2 related to host response and/or inflammation in neurological disorders, could be used as potential biomarkers of brain pathology." (PMID 24695528, 2014). "The exact mechanism behind the TIMP-1 activation of astrocytes is largely uncharted; understanding of the duality of TIMP-1 and astrocytic activation may lead to insights for novel treatments of neurological diseases and injuries." (PMID 39329731, 2024).
liver (9 papers, 2018 to 2025). "TIMP1 increases proliferation and metastasis in pancreatic and colorectal cancer." (PMID 35778451, 2022). "However, panose treatment failed to alleviate liver injury at this stage, as demonstrated by comparable plasma ALT and AST levels, Sirius Red–stained liver fibrosis scores, and mRNA expression of fibrotic markers (α-Sma, Col1a1, and Timp1) between PBS and panose treatment groups." (PMID 40478727, 2025). "Furthermore, serum levels of TIMP-1 were evaluated in recent studies, revealing that TIMP-1 might predominate over the effects of MMPs in the very early stages of CRC, and the TIMP-1 protein have been linked to the degree of malignancy, particularly in colorectal carcinogenesis." (PMID 30458003, 2018).
bacterial infection (5 papers, 2008 to 2023). "This is important because it demonstrates that microglia play a pivotal protective role in driving glial TIMP expression in two ways, first, by upregulating TIMP-2 in response to serum, and second, by facilitating astrocyte TIMP-1 expression is response to bacterial infection." (PMID 21631912, 2011). "In our previous study, TIMP-1 correlated with the total BVAS score before treatment and was less likely to be elevated in bacterial infections than CRP." (PMID 33743769, 2021).
immune dysfunction (5 papers, 2012 to 2025). "Future CRISPR-Cas9 studies targeting these upstream regulators will be essential to establish their causal roles in TIMP1-mediated metabolic-immune dysfunction." (PMID 41393260, 2025). "TIMP1 appears to sit at a critical node within this cycle, both responding to and amplifying both metabolic and immune dysfunction." (PMID 41393260, 2025). "Targeting TIMP-1 or its receptor is widely used in the treatment of immune disease." (PMID 27130446, 2016).
neurodegenerative disease (5 papers, 2017 to 2024). A disorder of the central nervous system characterized by gradual and progressive loss of neural tissue and neurologic function. "Furthermore, variations in the TIMP-1 gene have been established to influence the risk of neurodegenerative diseases and gene expression." (PMID 38891891, 2024). "The expression of TIMP‐1 had been reported to be increased in cerebrospinal fluid (CSF) of neurodegenerative diseases and significantly correlated with Alzheimer's disease (AD) biomarkers." (PMID 32431079, 2020). "Aberrant expression of TIMP‐1 was observed in brain tissue, CSF and plasma of neurodegenerative diseases." (PMID 32431079, 2020). "Furthermore, TIMP1 was found to reduce the number of neuronal cells in patients with neurodegenerative diseases who were exposed to ER stress." (PMID 33733597, 2021). "They hypothesized that TIMP‐1 played a potential role in neurodegenerative diseases." (PMID 32431079, 2020). "Concentrations of the MMP inhibitors TIMP1 and TIMP2 also increase in neurodegenerative disease states—which can be paradoxically accompanied by an increase in activity of the MMPs that they control." (PMID 31443560, 2019). "Thus, elevated CSF levels of TIMPs (TIMP-1 and TIMP-2) in neurodegenerative diseases, including HD, represent a compensatory attempt at regulating already elevated and uncontrolled MMP activity." (PMID 29459817, 2017).
infectious disease (4 papers, 2014 to 2022). A disorder directly resulting from the presence and activity of a microbial, viral, or parasitic agent in humans. "We measured the levels of MMP-8, MMP-9 and TIMP-1 by specific immunoassays previously found to be suitable for diagnosis and monitoring of systemic low-grade inflammation associated with cardiovascular and infectious diseases as well as other inflammatory states." (PMID 28407807, 2017). "Serum levels of TIMP1 in patients with AAV were significantly higher than those in patients with infectious diseases." (PMID 28962592, 2017). "Moreover, in contrast to CRP, serum levels of TIMP1 in patients with active AAV were significantly higher than those in patients with infectious diseases." (PMID 28962592, 2017). "In contrast, the serum levels of TIMP1, TKT, and CD93 were significantly higher in patients with active AAV than in those with infectious diseases." (PMID 28962592, 2017).
metabolic disorders (3 papers, 2018 to 2019). "MMP-9, TIMP-1, and MMP-9/TIMP-1 ratio correlated with biomarkers of inflammation, kidney and liver injury, coagulation, metabolic disorders, and disease severity scores." (PMID 29861795, 2018). "Moreover, mRNA expression of TIMP-1 and MMP-1 was separately down- and upregulated, respectively, indicating that the collagen metabolism disorder had been controlled." (PMID 31534523, 2019).
peripheral neuropathy (3 papers, 2018 to 2022). A disorder affecting the peripheral nervous system. "For such patients, measurement of the serum TIMP-1 may be helpful for diagnosing peripheral neuropathy." (PMID 36362162, 2022). "Thus, the spatial and temporal relation of the specific MMP-9 and TIMP-1 species and binding partners will determine the functional outcomes of their individual and joint activities in painful peripheral neuropathy." (PMID 29558999, 2018). "In addition, in facilities where NCSs cannot be performed or where a neurologist is absent, measurement of the serum TIMP-1 may be useful for diagnosing peripheral neuropathy." (PMID 36362162, 2022).
respiratory disease (3 papers, 2015 to 2022). "Additionally, the MMP-8 : TIMP-1 ratio can identify cases of respiratory disease, in which clinical signs and cytologic findings are almost unremarkable, which is very helpful, when examining horses in remission." (PMID 26770019, 2015).
retinopathy (3 papers, 2015 to 2023). "RANTES is a chemokine that is strongly related to retinopathy and angiopathy, and TIMP1 and TIMP2 play roles in the inhibition of EC morphogenesis." (PMID 37503820, 2023). "In addition, MMP-2, -3 and -10, and TIMP-1 levels were associated with macroalbuminuria, and MMP-2 was associated with proliferative retinopathy." (PMID 25848912, 2015). "Elevated circulating levels of MMP-2 and MMP-9 along with elevated levels of TIMP-1 were observed in patients with DR compared to diabetic patients without retinopathy." (PMID 34069322, 2021). "However, significant associations between plasma levels of MMPs and TIMP-1 on the one hand and CVD, albuminuria and retinopathy on the other hand were largely independent of LGI and ED, as these associations remained significant after adding the LGI and/or ED score to the model (Models 3, 4 and 5)." (PMID 25848912, 2015). "Linear regression analysis was applied to investigate differences in plasma levels of MMP-1, −2, −3, −9, −10, and TIMP-1 between patients with and without CVD, albuminuria or retinopathy." (PMID 25848912, 2015).
bone disorder (2 papers, 2022 to 2023). "We found a stable profile of mRNA expression for MMP-2 and 3, TIMP-2 and -3, and a slight decline for the MMP-1 and TIMP-1 and -2 profiles during the differentiation of ASCs to osteocytes, which predispose these cells to future therapy in bone disorders." (PMID 37428795, 2023).
brain) disease (2 papers, 2018 to 2020). "In exploratory analyses, we found associations of ADAMTS13 activity with levels of VEGF, MMP-3, Tenascin-C, and TIMP-1, which might indeed indicate involvement in vascular remodelling, and in any case encourage further study of ADAMTS13 in relation to vascular (brain) disease and neurodegeneration." (PMID 29615758, 2018).
hematologic malignancies (2 papers, 2017 to 2025). "FINC, PF4, and CXCL7 levels were significantly decreased in patients with hematologic malignancies, while TIMP1 levels were elevated in those with chronic liver disease." (PMID 40864331, 2025).
vasculopathy (2 papers, 2021 to 2024). "The fact that TGF-β1 was associated with TIMP-1 in both genotypes indicates that these molecules may play an important role in vascular remodeling and vasculopathy through extracellular matrix deposition." (PMID 33790690, 2021). "Markers of fibrosis (TIMP-1 and PIIINP) and vasculopathy (MMP-9) were additionally elevated." (PMID 38956476, 2024).
hematological cancers (1 paper, 2013). "Recent studies have suggested the clinical utility of TIMP1 as a biomarker and independent prognostic factor in breast, colorectal and several hematological cancers." (PMID 23522389, 2013).
TIMP1 also shares sentences with these, for which no sentence is quoted: chronic periodontitis (15 papers); skin aging (7); multiple myeloma (6); cystic fibrosis (4); essential hypertension (4); heart (4); acute liver failure (3); acute myocardial infarction (3); breast adenocarcinoma (3); delirium (3); ischemic cardiomyopathy (3); pneumonia (3); acne (2); acute lymphoblastic leukemia (2); acute myeloid leukemia (2); airway hyperresponsiveness (2); alcoholic liver diseases (2); ascending aortic aneurysms (2); brain edema (2); breast ductal carcinoma (2); bronchopulmonary dysplasia (2); carcinosarcoma (2); cholangiocarcinoma (2); chronic bronchitis (2); dysplasia (2); encephalitis (2); essential thrombocythemia (2); glomerular disease (2); Glomerular sclerosis (2); Huntington disease (2).
A further 191 diseases each share a sentence with TIMP1 in 2 papers or fewer.